WT1 (WT1 transcription factor)
Diseases named in the same sentence as WT1 in open-access papers (continued):
Sharing a sentence is not in itself a finding about the gene and the disease.
cancer (continued). "In addition, it was verified that WT1 protein peptides could also be presented on the cell surface to become a cancer-associated antigen." (PMID 36500358, 2022). "Therefore, loss of functional WT1 was thought to predispose for cancer development." (PMID 36818371, 2022). "Wilm’s Tumor protein 1 (WT1), a transcription factor that plays a role in urogenital development and tumor suppression, is a prime candidate for cancer immunotherapy." (PMID 40013133, 2025). "For example, WT1-specific antisense oligonucleotides have shown potential in preclinical models by reducing WT1 expression and impairing cancer cell growth." (PMID 40493404, 2025). "We retrieved frozen bone marrow DNA samples for all patients that presented at diagnosis with a WT1/ABL1 level lower than 250 at the three institutions of our comprehensive cancer and research network from 2013 to 2017." (PMID 40227798, 2025). "The safety and efficacy of the combined treatment strategy of infusion of Treg-depleted T lymphocytes and WT1 antigen-specific cancer immunotherapeutic in patients with WT1-positive AML are under evaluation (NCT01513109)." (PMID 40771826, 2025). "FLT3 was also found to be involved in transcriptional misregulation in cancer and its promoter region was bound by WT1 according to Genecards." (PMID 38944027, 2025). "This was corrected through IHC testing, which confirmed the mesothelial cell lineage (calreticulin-positive, WT-1-positive, D2-40-positive) and excluded cancer markers (e.g., PAX-8-negative)." (PMID 41395612, 2025). "Therapeutic TCRs for these two epitopes have been described and tested in clinical trials, highlighting the relevance of WT1-126 and WT1-37 epitopes in the context of anti-cancer TCR-T cell therapies." (PMID 39259326, 2025). "Many of these therapies are based on activation of WT1-specific T cells targeting cancer cells overexpressing the WT1 antigen." (PMID 39259326, 2025). "Antisense transcripts of TF genes such as SOX9 and WT1 have been shown to have functional roles in cancer." (PMID 41255714, 2025). "Researchers are exploring the use of various antigens in DC vaccines, including complex tumor lysates, synthetic MHC class I-restricted peptides, and mucin 1 peptide, a key antigen in cancer research, WT-1 TAA mRNA is another highly ranked antigen." (PMID 40382583, 2025). "Dysregulated methylation of WT1, PLEK2, MRAS, and RXRA in the twin with B‐ALL increases cancer susceptibility." (PMID 38970307, 2024). "The characteristic trait of high expression levels in cancer cells and low presence in normal tissues is the rationale for the use of the WT1 vaccination and makes the WT1 an appealing target for better outcomes." (PMID 38665761, 2024). "Curiously, TCGA-OV was the only TCGA dataset containing tWT1 expression, and correlated with the higher level of WT1 expression in this cancer type compared to others, where it was shown to promote EMT under hypoxic conditions." (PMID 38977895, 2024). "For instance, WT-1, widely used as an antigen for anti-cancer immunotherapy, is expressed not only in various cancer types but also in cancer-surrounding endothelial cells, stimulating angiogenesis." (PMID 38254898, 2024). "Upon activation, these lymphocytes induce apoptosis in cancer cells by specifically targeting those with increased WT1 levels." (PMID 38665761, 2024). "The eradication of cancer stem cells expressing WT1 that are resistant to chemotherapy and radiotherapy is a critical step in achieving a cure for cancer." (PMID 39737308, 2024). "This suggests a convergent evolution in cancer, where cancer cells from different species attempt to express a functional truncated version of WT1 through different mechanisms." (PMID 38977895, 2024). "In the oncological setting, WT1 expression has often been documented in the vasculature and stroma of various adult cancers." (PMID 38929778, 2024).
cancer (continued). "A new cancer vaccine clinical trial [NCT05964361] focuses on enhancing the body’s immune response by targeting the Wilms tumor 1 (WT1) protein." (PMID 39335494, 2024). "Several recent trials have evaluated cancer vaccines directed against WT1, including a phase II trial for advanced TETs." (PMID 38611047, 2024). "Despite being confronted with significant challenges, ongoing research into WT1 vaccines offers a promising future for cancer treatment, especially when it comes to treating AdPC, which calls for innovative approaches beyond current limitations." (PMID 38665761, 2024). "WT1 is known to be over-expressed in various human malignancies and is a key antigen of our mRNA-based DC cancer vaccine program." (PMID 38932353, 2024). "A completed clinical trial that studied DSP-7888, a cancer vaccine that induces WT1-specific T cells, showed improved survival in DIPG patients compared to controls (NCT02750891)." (PMID 38774284, 2024). "WT1 is expressed not only on the proliferating cells of almost all types of cancers but also on their quiescent stem cells." (PMID 39737308, 2024). "The advantage of using H/K-HELP-DCVAC is that antigen-pulsed activated DCs readily migrate to the TDLN and CD4+ and CD8+ T cells respond to DCs presenting WT-1 and survivin, which are expressed in most cancers, resulting in effective cancer therapy." (PMID 39411614, 2024). "This all-encompassing strategy seeks to reduce participant selection biases, improve generalizability, and offer a more detailed knowledge of the interplay between different chemotherapy regimens and WT1 cancer vaccines." (PMID 38665761, 2024). "This is because H/K-HELP-pulsed DCVAC is expected to be a good cancer treatment for inducing stronger Th1-dependent antitumor immunity against WT-1 and survivin common cancer antigens in addition to neoantigens released by radiotherapy-induced ICD." (PMID 39411614, 2024). "WT1 is overexpressed in several cancers, including TETs, and serves as an excellent TAA for the development of cancer vaccines." (PMID 38611047, 2024). "Various genes like Hsp70, eIF3i, and WT1 have been targeted by shRNA‐loaded liposomes and more studies are required to target additional molecular pathways responsible for cancer progression." (PMID 38919334, 2024). "Following their first interaction with WT1-expressing cancer cells, memory T cells (both central and effector memory T cells) continue to exist." (PMID 38665761, 2024). "The analysis detected many genetic variants and mutations in genes related to cancer, including CTNNB1 and WT1, which have been previously reported to be associated with WT." (PMID 38672648, 2024). "Cancer vaccines with WT1-derived epitopes have been investigated in several types of cancers including SGCs." (PMID 38539539, 2024). "One significant obstacle in the field of WT1 expression is its heterogeneity across various cancer types and even within individual tumors." (PMID 38665761, 2024). "IL15, known for its role in supporting natural killer cell function, promoting T cell memory formation, and enhancing immune response, is expected to enhance the immunogenicity of dendritic cells towards WT1-expressing cancer cells." (PMID 39335494, 2024). "The focus on the WT1 antigen is one of the noteworthy developments in the development of cancer vaccines." (PMID 38665761, 2024). "Namely, radiation-induced immunogenic cell death (ICD) activates antigen-presenting cells, which facilitate the induction of Th1 and CTL specific to neoantigen and common cancer-rejection antigens such as WT1 and survivin." (PMID 39411614, 2024). "Dendritic cells are commonly used as antigen-presenting cells, and the common cancer antigen Wilms' tumor 1 (WT1) is often used as their target antigen." (PMID 38143707, 2023). "As a few other cancers can show dual positivity, antibodies specific to mesothelial cells, namely WT1 and CK5, were also used in our study." (PMID 38026668, 2023).
cancer (continued). "A total of 150 intersection genes were observed between the DEGs of variant cancer epithelium (OCE) and normal tissue samples in GSE38666 and DEGs of Wt1 (−KTS)/ Wt1 (+KTS)." (PMID 36829196, 2023). "Here, we report a clinical trial of a biweekly WT1 tri-peptide-based vaccine for recurrent or advanced rare cancers." (PMID 36672344, 2023). "In this study, we conducted a clinical trial evaluating a biweekly WT1 tri-peptide-based vaccine for recurrent or advanced rare cancers." (PMID 36672344, 2023). "We analyzed the production of IgG Abs against the WT1 peptide (the first primary endpoint of this clinical trial) by monitoring the immune responses against WT1, the target antigen of the WT1 Trio cancer vaccine." (PMID 36672344, 2023). "Further mechanistic investigation of WT1 in transcription and signal transduction regulation will enhance our understanding of its complex roles in human cancers." (PMID 37667197, 2023). "DSP-7888 (adegramotide/nelatimotide) Emulsion is an investigational therapeutic cancer vaccine comprising three synthetic epitopes derived from WT1." (PMID 36138335, 2023). "After confirming that the WT1 vaccine inhibited the growth of cancer cells by inducing a strong immune response, a WT1 vaccine using serum from cancer patients was evaluated for the first time." (PMID 36826026, 2023). "BASP1 has been shown to act as an antioncogenic factor in a variety of cancers through its interaction with transcription factors such as WT1 and c‐myc." (PMID 37243901, 2023). "The WT1 gene is highly expressed in hematopoietic and various solid tumors, and cancer immunotherapies targeting WT1 protein have been developed." (PMID 37093243, 2023). "WT1 has been ranked as the most promising target antigen for therapeutic cancer vaccine development." (PMID 36138335, 2023). "Resveratrol, a potent antioxidant, anti-inflammatory, and cancer preventing agent, showed significant suppressions of WT1 protein expression, leukaemic cell proliferation, and cancer migration." (PMID 37296375, 2023). "Previous studies revealed that OCV-501 induces not only peptide-specific Th1 cells but also WT1-specific cytotoxic T-lymphocytes, suggesting its potential as a cancer vaccine." (PMID 37093243, 2023). "According to a 2009 report by the National Cancer Institute in the USA, the WT1 antigen ranked first among 75 common cancer antigens in an overall score of nine categories, including therapeutic efficacy, immunogenicity, cancer specificity, and expression." (PMID 38143707, 2023). "WT1 is overexpressed in many cancers and is correlated with poor prognosis in some types of cancers." (PMID 36760714, 2023). "The ability of CD4+ T cells to augment CD8+ T-cell antitumor responses is supported by data from a WT1-based therapeutic cancer vaccine containing only HLA-II antigens." (PMID 36138335, 2023). "Normal cancer antigens such as WT1 and hTERT loading to AML patients’ DCs are currently under clinical investigation." (PMID 37153761, 2023). "Due to the insufficient number of patients available for a traditional clinical trial, the trial was designed for rare cancers expressing shared target molecule WT1." (PMID 36672344, 2023). "Since then, immunotherapy targeting WT1 has been studied and clinical efficacies were shown in various cancer models." (PMID 36760714, 2023). "This work demonstrates the efficacy of the L-siRNA respiratory administration as a novel therapy to reduce pulmonary tumors and to increase survivability by silencing specific cancer oncogenes as WT1." (PMID 36960966, 2023). "Although many clinical trials of WT1 cancer vaccines using WT1 short peptides have been performed, the results of these clinical trials were disappointing." (PMID 37340017, 2023). "The selective cytotoxicity of WIP2W on WT1-overexpressing cancer cells and WT1-low-expressing normal cells, suggests the specific WT1 antagonistic effect and great biocompatibility of WIP2W." (PMID 37765274, 2023).
cancer (continued). "We also analyzed the DTH skin reaction to the WT1 peptide (the other primary endpoint of this clinical trial) by monitoring the immune response against WT1, the target antigen of the WT1 Trio cancer vaccine." (PMID 36672344, 2023). "DSP-7888 (adegramotide/nelatimotide) Emulsion, also known as Ombipepimut-S, is an investigational therapeutic cancer vaccine composed of three synthetic epitopes derived from WT1." (PMID 36138335, 2023). "WT1 was ranked as the most promising target antigen for cancer immunotherapy in 2009 by the US National Cancer Institute." (PMID 36760714, 2023). "These peptides encompass over 20 epitopes of the wild-type WT1 protein, thus triggering strong immune responses against multiple types of WT1-expressing cancers in patients with different HLA types." (PMID 36679991, 2023). "WT1 is often detected in various cancers, including leukemia, lung cancer, breast cancer, thyroid cancer, melanoma cancer, and OC." (PMID 36826026, 2023). "Most WT1 peptide-based vaccines previously tested in patients with cancer contained only human leukocyte antigen (HLA)-I epitopes and, therefore, only elicited WT1-specific cytotoxic (CD8+) T lymphocytes." (PMID 36138335, 2023). "Through a series of in vitro and in vivo preclinical experiments, we have shown that DSP-7888 Emulsion, a WT1-based therapeutic cancer vaccine, can induce HLA-restricted WT1-specific cytotoxic T cells and helper T cells." (PMID 36138335, 2023). "Wilms Tumor 1 (WT1) is an intracellular protein, and a zinc-finger transcription factor frequently associated with cancer." (PMID 37330575, 2023). "WT1 Trio cancer vaccine-induced IgG antibody production against WT1 peptides indicates the activation of WT1-specific B-lymphocyte lineage cells." (PMID 36672344, 2023). "When recruiting patients, we immunohistochemically examined the expression of WT1, the target antigen of the WT1 Trio cancer vaccine." (PMID 36672344, 2023). "This had led the National Cancer Institute to list Wt1 as one of the potential cancer antigens to be targeted by immunotherapy drugs." (PMID 36829196, 2023). "WT1 is one of the most studied immunotherapeutic targets in cancer, and hence, WT1-based peptide vaccines have been developed and evaluated in clinic with evidence of their potential safety and efficacy." (PMID 36679991, 2023). "As shown, the staining pattern of CK7 and WT1 in the representative PDOs is consistent and mimics the original primary carcinoma, displaying focal or patched expression in the primary carcinoma that is also represented in the corresponding PDOs." (PMID 37686015, 2023). "WT1cn reflects the proliferative potential of cancer cells or HSCs; however, several studies have shown that WT1 gene expression is detectable in mature granulocytes." (PMID 36467821, 2022). "More investigations are also required to examine if WT1 inhibition reduces the survival effects of HIF-PHIs in these cancers." (PMID 35465313, 2022). "Further investigations on the efficacy and safety of the WT1 peptide vaccine in other WT1-related cancers are required." (PMID 35465313, 2022). "Even though, currently, the evidence supporting this claim is limited, the wide spectrum of tumors manifesting WT1 expression has made it one of the most promising targets in cancer immunotherapy." (PMID 35453662, 2022). "Mutant antigens, testis-specific antigens, and pan-cancer antigens, such as WT1, have been selected as cancer vaccines." (PMID 36552770, 2022). "Other genes that are differentially expressed in Bhas 42 CTA by TPA treatment include RAN, MTHFD2, WT1, and AURORA-A, which are markers that cause cancer formation and malignant transformation in humans and laboratory animals." (PMID 35328637, 2022).
cancer (continued). "A recent study that used Wt1-dependent CreER-expressing mice for the lineage tracing of Wt1+ MCs identified MC-derived CAFs in the cancer stroma." (PMID 36233262, 2022). "The control of MC, especially when expressing Wt1 differentiation, is an important issue in the treatment of human diseases, such as inflammation, cancer, and injury, as well as PD." (PMID 36233262, 2022). "WT1 in concert with a variety of genes and proteins plays important roles in tumorigenesis and cancer metastasis." (PMID 35465313, 2022). "This evidence collectively suggests the crucial roles of HIFs and WT1 in modulating EMT in cancer hypoxia." (PMID 35465313, 2022). "Such TCRm-CAR Ts displayed direct cytotoxic activity against WT1+ cancer cell lines in vitro, while the scFv fusion antibody inhibited tumor growth in animal models of cancer, in part through Fc mediated effector functions." (PMID 36338746, 2022). "In a phase I clinical trial, WT-I vaccination activated WT-1-specific cytotoxic T lymphocytes (CTLs) and resulted in cancer regression with a good safety profile in 2 patients with BC with overexpression of the WT-1 gene and HLA-A*2402-possibility." (PMID 35734599, 2022). "Previous studies have shown that WT1 can promote cancer progression by regulating target genes, such as p21, SLUG, and CDH1." (PMID 35915803, 2022). "Despite the non-detection of EpCAM-negative cells, a green Alexa Fluor 488 fluorescence was detected in EpCAM+ cells, indicating a WT1 expression in cancer cells." (PMID 36293034, 2022). "The overexpression of WT1 in TETs provides an opportunity to develop cancer vaccines utilizing this TAA." (PMID 35565190, 2022). "Other cancers, such as leukemia and breast cancer, have been shown to overexpress wt1, making this gene an oncogene." (PMID 36412640, 2022). "Although phase I/II clinical trial has shown that Wilms tumor 1 (WT1)–targeted DC vaccine was a potential treatment in advanced cancer including GC, only three GC patients were included in the enrolled patients and only one GC patient was effective." (PMID 36225938, 2022). "This includes its reciprocal regulatory ties with NF-κB and WT1, and the more recent reports showing an involvement in regulatory circuits in cancer cells." (PMID 33917766, 2021). "To further investigate the anti-cancer contribution of WT1 targeting by miR-642a-5p, we transiently and stably overexpressed WT1 cDNA (WT1-203 isoform) in 22Rv1 and LNCaP PCa cells, and transfected these cells with 30 nM miR-642a-5p or miR-NC." (PMID 34504167, 2021). "Recent studies have described the WT1 protein as an oncogene because, in cancer, it regulates genes responsible for cell growth, apoptosis, and tumoral angiogenesis such as cyclin D1, Bcl-2, Bcl-xL, BFL1, c-myc, and VEGF." (PMID 34845427, 2021). "In recent years, several studies have demonstrated the presence of Wilms’ tumor 1 (WT1) protein within the cytoplasm in several benign and malignant tumors, suggesting its complex regulator activity in transcriptional/translational processes." (PMID 33445443, 2021). "Our results indicated the priority of the combination therapies of WT1 peptide vaccine and anti-PD-1 antibody in cure-oriented cancer immunotherapy." (PMID 34355173, 2021). "WT1 is an important therapeutic target, and a peptide vaccine has been developed for cancer treatment." (PMID 34692659, 2021). "Given our observation that Wt1 is expressed in immune cells in the context of cancer, it will be interesting to further identify an implication of Wt1 in immune responses in the context of cardiovascular diseases." (PMID 34299295, 2021).